SNORD14B (small nucleolar RNA, C/D box 14B)
Synonyms: U14B; U14; RNU14B
Gene: Small nucleolar RNA gene on chromosome 11 (17,075,779 to 17,075,868, reverse strand). Ensembl gene ENSG00000201403.
Gene Ontology:
Biological process: RNA processing
Cellular component: nucleolus
Homologues: Orthologues: pig SNORD14 (98% identical), rabbit SNORD14 (96% identical), mouse Snord14a (87% identical), rat Snord14a (87% identical), tropical clawed frog SNORD14 (81% identical), guinea pig SNORD14 (63% identical). Paralogues in human: SNORD14 (91% identical), SNORD14A (83% identical), SNORD14E (74% identical), SNORD14C (73% identical), SNORD14D (67% identical).